ENSG00000308507 (novel transcript)
Gene: Long non-coding RNA gene on chromosome 1 (120,844,228 to 120,850,459, forward strand). Ensembl gene ENSG00000308507.
Gene Ontology:
Molecular function: triplet codon-amino acid adaptor activity
Biological process: translation